NMI (N-myc and STAT interactor)
Description:
Acts as a signaling pathway regulator involved in innate immune system response. In response to interleukin 2/IL2 and interferon IFN-gamma/IFNG, interacts with signal transducer and activator of transcription/STAT which activate the transcription of downstream genes involved in a multitude of signals for development and homeostasis. Enhances the recruitment of CBP/p300 coactivators to STAT1 and STAT5, resulting in increased STAT1- and STAT5-dependent transcription. In response to interferon IFN-alpha, associates in a complex with signaling pathway regulator IFI35 to regulate immune response; the complex formation prevents proteasome-mediated degradation of IFI35. In complex with IFI35, inhibits virus-triggered type I IFN-beta production when ubiquitinated by ubiquitin-protein ligase TRIM21. In complex with IFI35, negatively regulates nuclear factor NF-kappa-B signaling by inhibiting the nuclear translocation, activation and transcription of NF-kappa-B subunit p65/RELA, resulting in the inhibition of endothelial cell proliferation, migration and re-endothelialization of injured arteries. Negatively regulates virus-triggered type I interferon/IFN production by inducing proteosome-dependent degradation of IRF7, a transcriptional regulator of type I IFN, thereby interfering with cellular antiviral responses (By similarity). Beside its role as an intracellular signaling pathway regulator, also functions extracellularly as damage-associated molecular patterns (DAMPs) to promote inflammation, when actively released by macrophage to the extracellular space during cell injury or pathogen invasion. Macrophage-secreted NMI activates NF-kappa-B signaling in adjacent macrophages through Toll-like receptor 4/TLR4 binding and activation, thereby inducing NF-kappa-B translocation from the cytoplasm into the nucleus which promotes the release of pro-inflammatory cytokines.
Tractability: Antibody: UniProt places it where antibodies can reach, with high confidence; its Gene Ontology location is reachable by antibodies, with medium confidence. PROTAC: UniProt records ubiquitination sites on it; ubiquitination databases record sites on it; its protein half-life has been measured.
Gene: Protein-coding gene on chromosome 2 (151,270,467 to 151,289,908, reverse strand). Ensembl gene ENSG00000123609.
Subcellular location: Cytoplasm; Nucleus; Secreted
Subcellular location (Human Protein Atlas): Cytosol; Nucleoplasm; Predicted to be secreted
Pathways (Reactome):
Disease: SARS-CoV-1 activates/modulates innate immune responses
Gene Ontology:
Molecular function: heat shock protein binding; identical protein binding; molecular adaptor activity; protein binding
Biological process: macrophage activation involved in immune response; negative regulation of cell population proliferation; negative regulation of innate immune response; negative regulation of non-canonical NF-kappaB signal transduction; positive regulation of non-canonical NF-kappaB signal transduction; positive regulation of receptor signaling pathway via STAT; response to heat; cell surface receptor signaling pathway via JAK-STAT; positive regulation of inflammatory response; positive regulation of innate immune response; response to virus; toll-like receptor 4 signaling pathway; regulation of innate immune response
Cellular component: cytoplasm; cytosol; extracellular region; membrane; nucleus
Genetic constraint (gnomAD): Loss-of-function variants: 14 observed, 14.97 expected, observed/expected ratio (o/e) 0.94, 90% interval 0.62 to 1.46. The upper end of that interval is the gene's LOEUF score, 1.46, which puts it in group 6 of 6, group 1 being the genes least tolerant of losing a copy. Missense variants: 181 observed, 207.7 expected, observed/expected ratio (o/e) 0.87, 90% interval 0.77 to 0.99. Synonymous variants: 64 observed, 72.49 expected, observed/expected ratio (o/e) 0.88, 90% interval 0.72 to 1.09.
Homologues: Orthologues: chimpanzee NMI (99% identical), macaque NMI (94% identical), guinea pig NMI (71% identical), rabbit NMI (69% identical), mouse Nmi (65% identical), rat Nmi (61% identical), pig NMI (59% identical), dog NMI (59% identical), tropical clawed frog nmi (33% identical). Paralogues in human: IFI35 (24% identical), RBM43 (15% identical).
Diseases named in the same sentence as NMI in open-access papers:
NMI is named in the same sentence as 23 diseases in open-access papers, as found by Europe PMC text mining. Sharing a sentence is not in itself a finding about the gene and the disease. The quoted sentences say what the papers report.
breast cancer (7 papers, 2014 to 2025). A primary or metastatic malignant neoplasm involving the breast. "However, the functions of NMI and its underlying molecular mechanisms as a tumor suppressor in breast cancer stem cells (BCSCs) remain unclear." (PMID 28492540, 2017). "Our results indicate that STAT5A, together with NMI protein expression in primary breast cancer tumors, is reduced compared to adjacent normal breast tissue." (PMID 34078871, 2021). "We observed that T47D breast cancer cells stably silenced for NMI expression showed significantly reduced activities of β-Casein promoter and STAT5 response element reporter." (PMID 34078871, 2021). "The in vivo study also validated that NMI knockdown promoted breast cancer growth by upregulating hTERT signaling in a mouse model." (PMID 28492540, 2017). "The expression of NMI was downregulated in breast cancer mammospheres compared with primary breast cancer and NMI was also downregulated in the CD44+CD24− cells compared with the CD44−CD24+ cell populations." (PMID 28492540, 2017). "NMI negatively regulated hTERT expression in breast cancer cells, and hTERT silencing or overexpression reversed the NMI silencing or overexpression-mediated changes in BCSCs traits in vitro and in vivo." (PMID 28492540, 2017). "NMI knockdown promotes CSCs expansion and tumorigenicity of breast cancer cells, while NMI overexpression inhibits CSCs properties." (PMID 28492540, 2017). "NMI knockdown upregulated hTERT expression while its overexpression downregulated hTERT in breast cancer cells, and the changes in CSCs traits and cell invasion ability mediated by NMI were rescued by hTERT." (PMID 28492540, 2017). "We also observed that silencing NMI expression from epithelial-like breast cancer cell lines induced molecular markers and morphological attributes of mesenchymal-like phenotype as well as promoted the invasive ability of these cells." (PMID 25174825, 2014). "Our observations provide the first clue that miR-29a and miR-29b are involved in negatively regulating the expression of NMI in breast cancer." (PMID 25174825, 2014). "Furthermore, we demonstrated that the interaction of YY1 protein with NMI and its involvement in NMI-mediated transcriptional regulation of hTERT in breast cancer cells." (PMID 28492540, 2017). "Hence, NMI overexpression significantly impaired CSCs expansion and tumorigenicity of breast cancer cells." (PMID 28492540, 2017). "Moreover, the involvement of YY1 protein in NMI-mediated transcriptional regulation of hTERT in breast cancer was identified and confirmed." (PMID 28492540, 2017). "Additionally, NMI knockdown also upregulated the expression of hTERT protein, while its overexpression downregulated the hTERT protein levels in breast cancer cells." (PMID 28492540, 2017). "To explore the function of NMI in BCSCs, we first analyzed the expression level of NMI in different human breast cancer cell lines by western blot and found that NMI displayed comparatively high expression in MCF7 and T47D while low expression in MDA-MB-231 (data not shown)." (PMID 28492540, 2017). "In breast cancer cells treated with low-concentration Teniposide, both IRF7 and NMI were significantly upregulated at the transcript and protein level." (PMID 38719798, 2024). "Co-immunoprecipitation assay also confirmed the interaction between of NMI and YY1 in different breast cancer cells." (PMID 28492540, 2017). "Our TCGA database analysis reveals concurrent expression of NMI and DRAM1 in breast cancer specimens." (PMID 26146406, 2015).
glioma (3 papers, 2015 to 2022). A benign or malignant brain and spinal cord tumor that arises from glial cells (astrocytes, oligodendrocytes, ependymal cells). "A recent study showed that NMI is a regulator of tumor proliferation which effects on glioma cell growth." (PMID 28077802, 2017). "Compared to 16 cases of normal tissues, the immunoreactivity of NMI was unequivocally elevated in human gliomas and increased according to WHO grades, while the highest expression of NMI was observed in GBM samples." (PMID 25669971, 2015). "Our TMA analyses revealed evident up-regulation of NMI protein in human glioma tissues, which was significantly increased according to tumor grade." (PMID 25669971, 2015). "The effects of NMI overexpression and deletion on glioma cells were also validated in another cell line, namely A172." (PMID 25669971, 2015). "Compared with the control shRNA infected cells, NMI silenced glioma cells showed a substantial increase in the percentage of the G0/G1 phase and marked decrease in the S phase." (PMID 25669971, 2015). "Considering that NMI has been reported to interact with various proteins, it is reasonable to assume that besides STAT1, other interactors of NMI may also be involved in development and progression of human glioma, which warrant further investigation." (PMID 25669971, 2015). "Furthermore, to confirm the interaction of NMI and STAT1, a co-IP assay was applied, in which U251 glioma cells were infected with lentiviruses carrying Flag-tagged NMI and STAT1 expressing vectors while empty vector served as a control." (PMID 25669971, 2015). "Together, these results suggest that knockdown of endogenous NMI could induce G0/G1 cell cycle arrest in glioma cells." (PMID 25669971, 2015). "We found that NMI and STAT1 showed dominant expression in the cytoplasm rather than the nucleus with both of the fluorescent signals merged with each other, indicating the co-localization of NMI and STAT1 within glioma cells." (PMID 25669971, 2015). "High GNAI, EMP3, TIMP1, ITGA5, and NMI while low PCDH7, CALCRL, and NFKBIA expressions could lead to poor prognoses in glioma patients." (PMID 35647198, 2022). "Collectively, these data suggest that NMI and STAT1 not merely interact with each other in glioma cells, but have a mutual regulation." (PMID 25669971, 2015). "Although NMI has been shown to interact with STAT1, a member of JAK/STAT pathway, none of that was reported in glioma." (PMID 25669971, 2015). "Previous finding has shown the interaction between NMI and STAT1, yet none was reported in glioma." (PMID 25669971, 2015).
breast tumors (2 papers, 2018 to 2024). "Therefore, we evaluated NMI immunohistochemically from primary breast tumors and their corresponding metastasis and found that NMI protein expression was significantly decreased in metastatic tissues." (PMID 38719798, 2024). "Additionally, the miR-29b family was found to target and negatively regulate the EMT regulator NMI, a gatekeeper of an epithelial phenotype, therefore inducing an aggressive mesenchymal phenotype in breast tumours." (PMID 30323900, 2018).
ovarian carcinoma (2 papers, 2018 to 2022). A malignant neoplasm originating from the surface ovarian epithelium. "NMI is an important component of a transcription factor complex that allows for the continuous activation of telomerase in breast and ovarian cancer, and participates in the regulation of bradykinin BDKRB2 and MAPK/ERK pathways, thus mediating tumor progression and metastasis." (PMID 36042374, 2022).
endometriosis (1 paper, 2024). The growth of functional endometrial tissue in anatomic sites outside the uterine body. "To explore NMI’s involvement in endometriosis progression in depth, we examined the RNA expression profiles of NMI knockdown (NMI KD) in IHESC cells and their respective controls." (PMID 39125716, 2024). "Therefore, NMI is a novel endometriosis suppressor, enhancing apoptosis and inhibiting proliferation and cell adhesion of endometrial cells upon IFN exposure." (PMID 39125716, 2024). "Although the precise role of NMI in the progression of endometriosis remains unclear, our study has identified NMI’s function within this context: NMI acts as a suppressor of endometriosis." (PMID 39125716, 2024). "Moreover, NMI knockdown in IHESCs stimulated ectopic lesions’ growth in mouse endometriosis models." (PMID 39125716, 2024). "The downregulation of NMI facilitates the avoidance of IFNA-induced cell death signaling and amplifies IFNA non-canonical pathways within endometrial stromal cells, thereby furthering the progression of endometriosis." (PMID 39125716, 2024). "Therefore, NMI knockdown effectively suppressed the phosphorylation of necroptosis components upon IFNA treatment and hindered IFNA-induced necroptosis in endometrial stromal cells, potentially contributing to the progression of endometriosis." (PMID 39125716, 2024). "Given that NMI knockdown adversely affected ISGF3 signaling in endometrial stromal cells, we explored whether NMI knockdown could also inhibit necroptosis in these cells, potentially facilitating the progression of endometriosis." (PMID 39125716, 2024). "Therefore, the downregulation of NMI activates AKT signaling, enhancing endometriosis progression." (PMID 39125716, 2024).
glioblastoma (1 paper, 2021). The most malignant astrocytic tumor (WHO grade IV). "Feng and colleagues showed pUL23 interacts with NMI following HCMV infection of human glioblastoma U251 cells, sequestering NMI to the cytoplasm." (PMID 34440891, 2021).
invasive breast carcinoma (1 paper, 2015). A carcinoma that infiltrates the breast parenchyma. "We have previously reported that expression of NMI (N-myc and STAT interactor) is compromised in invasive breast cancers." (PMID 26146406, 2015).
melanoma (1 paper, 2023). A malignant, usually aggressive tumor composed of atypical, neoplastic melanocytes. "The overexpression of NMI inhibits Wnt/β-catenin signaling, reducing melanoma invasion and metastasis." (PMID 37762054, 2023).
Obesity (1 paper, 2024). Accumulation of substantial excess body fat. "These communities may potentially interact with genes, including COL6A6 and NMI, thereby influencing the onset and progression of obesity." (PMID 38399773, 2024).
renal malignant tumors (1 paper, 2017). "It has been demonstrated that NMI is widely expressed in fetal and adult tissues, and is overexpressed in multiple cell lines derived from hematolymphoid, hepatic and renal malignant tumors." (PMID 28077802, 2017).
renal tumors (1 paper, 2017). "Specifically, the transcript expressions of AKR1C1, S100A2, PLAU, SLC3A2, TBC1D2, and WIZ were decreased, while expressions of TGM2, SLC7A5, and NMI were increased in renal tumors when compared with non-tumorous control samples." (PMID 29272308, 2017).
Sepsis (1 paper, 2017). Sepsis is defined as life-threatening organ dysfunction caused by a dysregulated host response to infection. "NMI deficiency reduces inflammatory responses and mortality in mouse models of sepsis and liver injury." (PMID 29038465, 2017). "Thus, NMI and IFP35 may serve as early molecule marker for the diagnosis of sepsis." (PMID 29038465, 2017).
stomach neoplasm (1 paper, 2017). "Our latest study showed that NMI promotes the interaction between NF-κB/p65 and histone deacetylases (HDACs) and inhibits the acetylation and transcriptional activity of p65, thus inhibiting cell migration and invasion in stomach neoplasm." (PMID 29109532, 2017).
tumor (14 papers, 2014 to 2024). "NMI is an interferon-inducible protein participating in various cellular activities and has been involved in the process of tumorigenesis and tumor progression." (PMID 37730697, 2023). "The expression of NMI was closely related to the unique molecular and immunotyping, diagnosis and prognosis of various tumor tissues." (PMID 36506566, 2022). "GPC3 was significantly down-regulated in tumor tissue in all data sets, while NMI was significantly up-regulated." (PMID 35710585, 2022). "In conclusion, our results show that NMI is a novel promotor of tumor growth, invasion and metastasis of HCC by inducing its downstream target BDKRB2 expression and activating MAPK/ERK signaling pathway." (PMID 28077802, 2017). "NMI is a protein identified to interact with a variety of proteins involved in tumor development, progression, inflammation and immune regulation." (PMID 25669971, 2015). "NMI, is a protein that play critical roles in tumor growth, progression, and metastasis." (PMID 30356407, 2018). "Normal (uninvolved) breast tissues showed elevated protein expression for NMI and STAT5A compared to their matched primary tumor tissues." (PMID 34078871, 2021). "The difference in expression comparing tumor and normal tissues were found to be significant in eight genes (PLAU, EGR1, IL6, EGFR, EZH2, BMP4, CCNB1, NMI)." (PMID 34077304, 2021). "We found that only ERK1/2 phosphorylation level obviously increased in Huh7 cells after up-regulation of NMI; and in contrast, significantly decreased phosphorylation levels of ERK1/2 in stable NMI silencing HCC-LM3 cells as well as their corresponding subcutaneous tumor tissues." (PMID 28077802, 2017).
cancer (7 papers, 2017 to 2024). A tumor composed of atypical neoplastic, often pleomorphic cells that invade other tissues. "Additionally, BJIKT reduced the expression of NMI, a gene associated with cancer cell proliferation." (PMID 39459546, 2024). "After NMI knockdown, the expression levels of MAPK signaling pathway members, including Raf1, MAPK11, MAP3K14 and MAP3K2, which are associated with cancer invasion and metastasis, were obviously decreased HCC-LM3." (PMID 28077802, 2017). "In addition, the expression of ZHX3 was found to be inversely related with the expressions of NMI and ARPC5, which have been associated with proliferation and motility of cancer cells, respectively." (PMID 28152006, 2017). "N-Myc and STAT Interactor protein (NMI) was initially discovered as a protein that interacts with various STATs; however, the relevance of these interactions to normal mammary development and cancer was not known." (PMID 34078871, 2021).
infection (4 papers, 2015 to 2025). The state of being infected such as from the introduction of a foreign agent such as serum, vaccine, antigenic substance or organism. "First, NMI stably overexpressed or silenced U251 and U87 cells were established by lentiviruses infection, while the empty vector (vector) or shRNA targeting LacZ (shLacZ) served as control groups respectively." (PMID 25669971, 2015). "Evidence for NMI and IFI35 (in M2) indicates that they function as damage-associated molecular patterns in the extracelluar space, mediating proinflammatory responses to cellular infection and damage through the activation of the nuclear factor-κB in the Toll-like receptor 4 signalling pathway." (PMID 40656995, 2025). "Of the ISGs IFN-γ, IRF5, NMI, and IRF8, only the expression of IFN-γ changed during the course of infection." (PMID 39104769, 2024).
NMI also shares sentences with these, for which no sentence is quoted: actinic keratosis (1 paper); colon cancer (1); Fanconi anemia (1); HCMV infection (1); HIV-1 infection (1); lung carcinoma (1); lung squamous cell carcinoma (1).